KCNK7 (potassium two pore domain channel subfamily K member 7)
Description:
Probable potassium channel subunit. No channel activity observed in vitro as protein remains in the endoplasmic reticulum. May need to associate with an as yet unknown partner in order to reach the plasma membrane.
Synonyms: K2p7.1; TWIK3
Tractability: Small molecule: it belongs to a druggable protein family. Antibody: its Gene Ontology location is reachable by antibodies, with high confidence; UniProt predicts a signal peptide or a membrane-spanning region; the Human Protein Atlas places it where antibodies can reach.
Gene: Protein-coding gene on chromosome 11 (65,592,836 to 65,595,996, reverse strand). Ensembl gene ENSG00000173338.
Subcellular location: Membrane
Subcellular location (Human Protein Atlas): Plasma membrane
Pathways (Reactome):
Muscle contraction: Phase 4 - resting membrane potential
Neuronal System: Tandem of pore domain in a weak inwardly rectifying K+ channels (TWIK)
Gene Ontology:
Molecular function: potassium channel activity; potassium ion leak channel activity
Biological process: potassium ion transport; potassium ion transmembrane transport
Cellular component: plasma membrane; membrane
Genetic constraint (gnomAD): Loss-of-function variants: 14 observed, 16.36 expected, observed/expected ratio (o/e) 0.86, 90% interval 0.56 to 1.34. The upper end of that interval is the gene's LOEUF score, 1.34, which puts it in group 5 of 6, group 1 being the genes least tolerant of losing a copy. Missense variants: 385 observed, 348.9 expected, observed/expected ratio (o/e) 1.1, 90% interval 1.01 to 1.2. Synonymous variants: 188 observed, 169.8 expected, observed/expected ratio (o/e) 1.11, 90% interval 0.98 to 1.25.
Homologues: Orthologues: chimpanzee KCNK7 (99% identical), macaque KCNK7 (93% identical), pig KCNK7 (83% identical), dog KCNK7 (80% identical), guinea pig KCNK7 (79% identical), mouse Kcnk7 (79% identical), rat Kcnk7 (74% identical), Drosophila melanogaster CG34396 (25% identical), Caenorhabditis elegans twk-46 (23% identical), Caenorhabditis elegans twk-21 (22% identical), Drosophila melanogaster CG42340 (22% identical), Drosophila melanogaster CG42594 (22% identical), and 13 more. Paralogues in human: KCNK1 (40% identical), KCNK6 (33% identical), KCNK4 (26% identical), KCNK10 (25% identical), KCNK2 (24% identical), KCNK15 (22% identical), KCNK16 (22% identical), KCNK12 (21% identical), KCNK3 (21% identical), KCNK9 (21% identical), KCNK17 (20% identical), KCNK5 (19% identical), and 2 more.
Diseases named in the same sentence as KCNK7 in open-access papers:
KCNK7 is named in the same sentence as 9 diseases in open-access papers, as found by Europe PMC text mining. Sharing a sentence is not in itself a finding about the gene and the disease. The quoted sentences say what the papers report.
melanoma (2 papers, 2019 to 2021). A malignant, usually aggressive tumor composed of atypical, neoplastic melanocytes. "Moreover, KCNK7 was rather highly transcribed in both cell lines, consistent with data on human melanoma samples." (PMID 34445066, 2021). "Such five genes (namely, SCNN1A, GJB3, KCNK7, GJB1, KCNN2) are novel potential melanoma markers or molecular targets, never previously related to melanoma." (PMID 30934896, 2019). "Five such genes (namely: SCNN1A, GJB3, KCNK7, GJB1, KCNN2) were identified as potential strong melanoma markers that had never been identified before." (PMID 30934896, 2019).
breast carcinoma (1 paper, 2022). "Expression of KCNK7 was negatively correlated with CD8+ T cell level, while KCNK9 expression was positively correlated with CD8+ T cell level in breast cancer." (PMID 35656548, 2022).
Hypertension (1 paper, 2023). The presence of chronic increased pressure in the systemic arterial system. "The methylation site cg21033440 upstream of KCNK7 contributed to hypertension (β = 0.01, p = 3.8e−11) by increasing the expression of this gene (β = 0.14, p = 8.9e−8)." (PMID 37274792, 2023). "The analyses revealed positive associations between the expression of KCNK7, FDFT1-NEIL2 locus and hypertension." (PMID 37274792, 2023). "It remains to be investigated how KCNK7 contributes to hypertension through lipids." (PMID 37274792, 2023). "KCNK7 mediated the impact of cg21033440-lipids on hypertension." (PMID 37274792, 2023).
thyroid cancer (1 paper, 2020). "However, KCNK1, KCNK6, KCNK7, KCNK9, KCNK10, KCNK13 and KCNK16 mRNA expressions were not related to the prognosis of patients with thyroid cancer." (PMID 32742463, 2020).
tumor (3 papers, 2019 to 2025). "The data showed that mRNA levels of KCNK7, KCNK9 and KCNK10 correlated inversely with tumor differentiation degree." (PMID 31581133, 2019). "Moreover, a total of 7 KCNKs were found to be closely related to the tumor stage, which were KCNK1, KCNK2, KCNK5, KCNK6, KCNK7, KCNK19, and KCNK15." (PMID 32742463, 2020).
cancer (2 papers, 2019 to 2021). A tumor composed of atypical neoplastic, often pleomorphic cells that invade other tissues. "The data show that mRNA expression of KCNK1, KCNK7, and KCNK9 is upregulated in cancer tissues while KCNK2, KCNK3, KCNK5, KCNK10, KCNK13, KCNK15, and KCNK17 levels are decreased compared to controls." (PMID 31581133, 2019).
KCNK7 also shares sentences with these, for which no sentence is quoted: asthma (1 paper); atrial fibrillation (1); papillary thyroid carcinoma (1).